LINC01140 (long independently transcribed non-coding RNA 1140)
Synonyms: FLJ41676
Gene: Long non-coding RNA gene on chromosome 1 (87,129,765 to 87,169,198, forward strand). Ensembl gene ENSG00000267272.
Diseases named in the same sentence as LINC01140 in open-access papers:
LINC01140 is named in the same sentence as 8 diseases in open-access papers, as found by Europe PMC text mining. Sharing a sentence is not in itself a finding about the gene and the disease. The quoted sentences say what the papers report.
breast carcinoma (2 papers, 2021 to 2023). "LINC01140 was found to be specifically expressed in lung and breast cancer compared to normal tissues." (PMID 37021001, 2023). "Only high expression of LINC01128, CCDC18-AS1, SH3BP5-AS1, HOTAIRM1, LINC01140, SGMS1-AS1, LINC01578 or LINC00667 had favorable prognosis in breast cancer." (PMID 34828282, 2021). "Mechanistic exploration revealed that a potential ncRNA-mRNA axis, involving LINC01128/LINC01140/SGMS1-AS1/LINC00667-miR-137/miR-429-BCL2, might be partially responsible for MUC14′s functions in breast cancer." (PMID 34828282, 2021).
bladder cancer (1 paper, 2020). "To validate the specific effect of LINC01140 on the aggressiveness of bladder carcinoma cells and the development of MIBC, we transfected si-LINC01140 to generate LINC01140 knockdown in T24 cells, and performed real-time PCR to verify the transfection efficiency." (PMID 33234721, 2020). "Similarly, culture with si-LINC01140-CM inhibited macrophage M2 polarization, indicating that LINC01140 might cooperate with FGF9 to modulate macrophage M2 polarization in bladder cancer, therefore affecting cancer cell aggressiveness." (PMID 33234721, 2020). "In conclusion, LINC01140, miR-140-5p, and FGF9 form a lncRNA-miRNA-mRNA axis that modulates the bladder cancer phenotype, affects macrophage M2 polarization through the tumor microenvironment, and in turn affects bladder cancer cell aggressiveness." (PMID 33234721, 2020). "Thus, LINC01140 might relieve miR-140-5p-induced inhibition of FGF9 by acting as a ceRNA, therefore affecting macrophage M2 polarization in bladder cancer." (PMID 33234721, 2020).
gastric cancer (1 paper, 2025). A primary or metastatic malignant neoplasm involving the stomach. "A previous study identified the lncRNA-miRNA-mRNA axis involving LINC01140, miR-140-5p, and FGF9, which regulates gastric cancer phenotypes and impacts cell aggressiveness." (PMID 40696350, 2025).
glioma (1 paper, 2021). A benign or malignant brain and spinal cord tumor that arises from glial cells (astrocytes, oligodendrocytes, ependymal cells). "Another work showed LINC01140 could promote glioma progression via regulating miR-199a-3p/ZHX1 axis." (PMID 33613672, 2021).
lung carcinoma (1 paper, 2021). "LINC01140 promotes the progression and tumor immune escape in lung cancer." (PMID 35127712, 2021).
osteosarcoma (1 paper, 2022). A usually aggressive malignant bone-forming mesenchymal neoplasm, predominantly affecting adolescents and young adults. "Several studies have found that lncRNAs play an important role in tumor progression, such as the down-regulation of linc01140, which inhibits proliferation and the invasion of osteosarcoma by targeting the miR-139-5p/HOXA9 axis." (PMID 36135086, 2022).
tumor (4 papers, 2020 to 2022). "This may be caused by the tissue specificity of LINC01140, suggesting that LINC01140 may operate as a tumor suppressor or progenitor in different tumor types." (PMID 36299824, 2022). "LINC01140 overexpression diminished BC cell viability, migration, and tumor growth and facilitated apoptosis." (PMID 36299824, 2022). "Furthermore, in the present study, I found that the overexpression of LINC01140 inhibited the malignant behavior of BC cells in vitro and reduced tumor growth in nude mice xenografts." (PMID 36299824, 2022).
cancer (3 papers, 2018 to 2022). A tumor composed of atypical neoplastic, often pleomorphic cells that invade other tissues. "LINC01140 is a potential regulator of cancer drive or containment in different tumors." (PMID 36299824, 2022). "Moreover, it was also found some cancer‐specific lncRNAs, such as LINC01140, LINC00261, ABHD11‐AS1, and TINCR,58, 59, 60, 61 served as important biomarkers in other different cancer types as well." (PMID 30318850, 2018).